ABCB1 (ATP binding cassette subfamily B member 1)
Diseases named in the same sentence as ABCB1 in open-access papers (continued):
Sharing a sentence is not in itself a finding about the gene and the disease.
cancer (continued). "CAR is a substrate of ABCB1 (angiotensin-binding cassette B1), one of the ABC family of transporters responsible for multidrug resistance by efflux of anticancer drugs, a mechanism of action that leads to failure of cancer treatment if the medication is administered systemically." (PMID 40732359, 2025). "In addition to ABCB1, increased resistance to DTX is correlated to an upregulated expression of the ABCC3 ATP binding cassette gene, which ultimately diminishes the efficacy of cancer treatment." (PMID 40385549, 2025). "Thus, Def appears to effectively disrupt processes central to cancer progression, such as metastasis and chemoresistance, potentially through its multifaceted impact on EGFR, ABCB1, and NDRG1 pathways, in support of our initial hypothesis." (PMID 39457585, 2024). "Interestingly, the genes for sorcin and ABCB1 (the most significant ATP-dependent drug efflux pump) are located near each other on chromosome 7 and can be co-amplified, leading to their simultaneous overexpression in MDR cancer cells." (PMID 39199583, 2024). "Furthermore, immunoassays for HTC were developed to distinguish cancer cells from stromal cells using the CK8/18 antibody cocktail and to distinguish cells with a multidrug-resistant phenotype from sensitive cells using the ABCB1, ABCC1 and ABCG2 antibodies." (PMID 39337925, 2024). "Thus, unraveling the mechanisms of MDR holds promise for innovating cancer models and antitumor targeted strategies, since inhibiting the P-glycoprotein (P-gp)/ABCB1 protein is not always an effective approach given the associated treatment toxicity." (PMID 39272999, 2024). "ABCB1, the key member of ATP-binding cassette (ABC) transporters, is related to exporting bound toxins out of the cell and could contribute to multidrug resistance in cancers subsequently." (PMID 38778348, 2024). "Interestingly, several compounds that were identified as ABCB1 inhibitors in different cancers failed to sensitize PDAC cells in our screen (i.e., erlotinib, imatinib, and nilotinib)." (PMID 38163893, 2024). "Furthermore, the efficacy of HS-173 could be recovered through inhibiting the drug-efflux function of ABCB1 and ABCG2 in multidrug-resistant cancer cells." (PMID 37048130, 2023). "Knowing that ABCB1 and ABCG2 could reduce the cytotoxicity of HS-173 in cancer cell lines, we next examined the impact of ABCB1 and ABCG2 on G2/M cell cycle arrest and apoptosis induced by HS-173, which are characteristic effects of HS-173 treatment in human cancer cell lines." (PMID 37048130, 2023). "Thus, there is still a reason to develop more efficacious and non-toxic ABCB1 inhibitors in order to reverse MDR in cancer treatment." (PMID 37233508, 2023). "While further investigation is required to understand the mechanisms of acquired resistance in patients treated with furmonertinib, our results indicate that the overexpression of ABCB1 or ABCG2 is unlikely to play a significant role in the development of resistance to furmonertinib in cancer cells." (PMID 37762275, 2023). "Therefore, targeting CD44 could represent a potential therapeutic strategy to overcome drug resistance for cancer cells overexpressing both CD44 and ABCB1." (PMID 36694209, 2023). "We demonstrated that the drug transport activity of ABCB1 and ABCG2 could extensively lower the intracellular accumulation of HS-173 and consequently reduce its ability to induce G2/M phase cell cycle arrest and apoptosis in human cancer cells." (PMID 37048130, 2023). "Finally, voruciclib, one of the CDK4/6i with anticancer effects, in combination with the BRAF inhibitor vemurafenib in advanced BRAF-mutant melanoma or with the proteasome inhibitor bortezomib in TNBC xenografts was found to antagonize ABCB1- and ABCG2-mediated multidrug resistance in cancer cells." (PMID 37835528, 2023). "This difficulty in adding ABCB1 inhibitors to existing regimens may stem from patients not being selected based on whether or to what extent ABCB1 is expressed in their cancer." (PMID 37438132, 2023).
cancer (continued). "Furthermore, we found that the effect of HS-173 on G2/M cell-cycle arrest and apoptosis was substantially reduced in ABCB1-overexpressing KB-V1 and ABCG2-overexpressing S1-MI-80 cancer cell lines when compared to what was observed with their respective parental cell lines." (PMID 37048130, 2023). "This, in turn, led to an elevated proapoptotic and cytotoxic activity of Dx towards a series of tumor cell lines, and also is suggested the main reason for partial circumvention of ABCC1 and ABCB1-driven resistance of cancer cells in vitro by Dx-PC-NSE, but not Dx-PC." (PMID 36986696, 2023). "As the overexpression of ABCB1 and ABCG2 is known to be a common mechanism responsible for the development of drug resistance in cancer cells, the purpose of this study is to determine whether HS-173 is susceptible to efflux in human cancer cells induced by ABCB1 and ABCG2." (PMID 37048130, 2023). "However, no band for the ABCB1 protein was obtained for the SW620 parental cancer cells, as they did not overexpress the ABCB1 transporter." (PMID 35350768, 2022). "However, in contrast to the previous findings, PD 173074 failed to re-sensitize ABCB1-overexpressing HCC 1806 cancer cells to PTX and Dox." (PMID 35327403, 2022). "Previous studies demonstrated that reversal of MDR phenotype in cancer cells might be due to the lowered expression of the ABCB1 by the tested compound and was not due to the direct inhibition of P-gp transporter." (PMID 35327403, 2022). "Although up-regulation of ABCB1 expression is expected to occur following exposure of cancer cells to DTX, thus underpinning acquisition of resistance to chemotherapy, high levels of expression of ABCB1 may also contribute to intrinsic resistance to DTX in chemo-naïve tumors." (PMID 35721223, 2022). "To determine whether ITZ was able to overcome DTX resistance unrelated to ABCB1 upregulation, we analyzed the DTX sensitivity data from the Genomic of Drug Sensitivity in Cancer project platform (GDSC1 dataset) to identify cell lines with substantial intrinsic DTX resistance (IC50 > 0.1 μM)." (PMID 35721223, 2022). "Therefore, CDK6 may be potential and secure targets for reversing ABCB1-mediated MDR, since its overexpression has been shown to stimulate cancer cell proliferation." (PMID 35459184, 2022). "Most known cancer cells have increased PIK3CA expression or more active PIK3CA which may lead to enhanced cell survivability, proliferative or anti-apoptosis ability, and overexpression of ABCB1 as we reported." (PMID 35459184, 2022). "In addition, ZEB1 may directly bind and thereby regulate the expression of multiple cancer stem cell markers including MYC and ABCB1." (PMID 35404029, 2022). "Therefore, the aim of this study was to investigate the impact of ABCB1 and ABCG2, two of the most common mechanisms of resistance to conventional and molecularly targeted anticancer drugs, on the efficacy of citarinostat in human cancer cell lines." (PMID 33807514, 2021). "Therefore, we investigated whether the activity of citarinostat is also affected by the drug efflux function of ABCB1 and ABCG2 in human cancer cell lines in a similar manner as ricolinostat." (PMID 33807514, 2021). "It is generally known that the overexpression of ABCB1 could induce MDR in some but not all types of cancer cells." (PMID 34572328, 2021). "Scientists found that NOB not only increased the accumulation of chemotherapy drugs in ABCB1-overexpressed cancer cells by inhibiting p-gp but also inhibited the Nrf2/Akt/ERK pathway, thereby enhancing the anticancer effect of paclitaxel in drug-resistant cancer cells." (PMID 34257674, 2021). "Multidrug-Resistant (MDR) cancers attenuate chemotherapeutic efficacy through drug efflux, a process that transports drugs from within a cell to the extracellular space via ABC (ATP-Binding Cassette) transporters, including P-glycoprotein 1 (P-gp or ABCB1/MDR1)." (PMID 34959691, 2021).
cancer (continued). "It is well known that a major mechanism of resistance in cancer cells is the overexpression of P-gp, also known as multidrug resistance protein 1 (MDR1) or ABCB1, which belong to ATP-binding cassette (ABC) transporters and could efflux the chemotherapeutic agents out of cells." (PMID 34856955, 2021). "In addition, 3f was no substrate of the cancer drug resistance associated drug efflux transporter Pgp/MDR1/ABCB1 (permeability glycoprotein, multidrug resistance protein 1, ATP-binding cassette sub-family B member 1)." (PMID 35582221, 2020). "Given the lack of Food and Drug Administration (FDA)-approved treatment for multidrug-resistant cancers, we explored the prospect of repurposing erdafitinib, the first fibroblast growth factor receptor (FGFR) kinase inhibitor approved by the FDA, to reverse MDR mediated by ABCB1." (PMID 32466597, 2020). "However, the mutations in ABCB1, ABCA1, ABCC1 and ABCG2 did not affect overall cancer survival rates as determined by log-rank tests (all P-values < 0.05)." (PMID 34541464, 2020). "Three ABC transporter proteins, P-glycoprotein (P-gp, MDR1, ABCB1), multidrug resistance protein 1 (MRP1, ABCC1), and breast cancer resistance protein (BCRP, ABCG2), have been shown to play a role in multidrug resistance of various types of cancers like OC, breast, lung, colon and others." (PMID 32257947, 2020). "Finally, sapitinib did not significantly alter the cytotoxic efficacy of cisplatin and oxaliplatin, two anti-cancer drugs that are not substrates for the ABCB1 transporter." (PMID 33163405, 2020). "Therefore, the EC16-1/saporin nanocomplex represents a novel anticancer strategy, not only for cancer patients with non-resistant tumor but also for patients with ABCB1 or ABCG2 drug-resistant cancers." (PMID 32098067, 2020). "The effects of dietary rosemary on the activity of the human drug efflux transporter P-glycoprotein (MDR1, ABCB1) and multidrug resistance protein 1 (MRP1, ABCC1) were explored by employing P-glycoprotein-overexpressing hMRP1 gene-transfected KB/MRP cells and human cancer KB-C2 cells." (PMID 32532056, 2020). "Additionally, miR-27a-3p affects drug sensitivity and the resistance of cancer cells, as its upregulation promotes the expression level of ABCB1/MDR1 gene, but it has not been studied in relation to SLC transporters up to date." (PMID 32111097, 2020). "However, this is unlikely as the incubation of SW620/Ad300 cancer cells with 5 μM of sapitinib for 72 h did not significantly alter the subcellular distribution of the ABCB1 transporter compared to cells incubated with vehicle." (PMID 33163405, 2020). "Moreover, our data suggest that ABCB1 is not a major mechanism of resistance to erdafitinib in cancer cells." (PMID 32466597, 2020). "Therefore, there is urgency to develop effective, targeted, and nontoxic ABCB1 inhibitors to reverse MDR in cancer." (PMID 32903706, 2020). "Notably, nab-paclitaxel, an HSA nanoparticle-based preparation of paclitaxel (another ABCB1 substrate), which is approved for the treatment of different forms of cancer, had previously been shown not to avoid ABCB1-mediated drug efflux." (PMID 31501742, 2019). "In addition, this acquisition of MDR phenotype did not involve the exchange or induction of mRNA, because there was no significant alteration in the expression of ABCB1 mRNA in sensitive cancer cells." (PMID 31830995, 2019). "In contrast, the protein expression of ABCB1 and ABCG2 in multidrug-resistant cancer cells was unaffected by TMP195 for 72 h, indicating that the downregulation of ABCB1 or ABCG2 does not play a significant role in the chemosensitization of multidrug-resistant cancer cells by TMP195." (PMID 31905792, 2019).
cancer (continued). "Furthermore, ABCB1 and ABCG2 can co-exist on the surface of many multidrug resistant cancer cells." (PMID 30544754, 2018). "Therefore, the different sized Ru@MSNs could overcome MDR by inhibiting ABCB1 and ABCG2, and consequently enhancing DNA damage mediated cancer cell apoptosis." (PMID 29334793, 2018). "Moreover, there was no significant alteration of insensitivity of cancer cells to cisplatin, which was neither an ABCB1 nor ABCG2 substrate." (PMID 30425643, 2018). "Similarly, some studies concluded that lapatinib reverses ABCB1- and ABCG2-mediated MDR by directly inhibiting their transport function, contributing to the possibility of co-administration with lapatinib treated MDR cancer patient in clinic." (PMID 29455646, 2018). "In further support of the concept that hypoxia promotes cancer stemness, we found that hypoxic challenge resulted in a significant increase in the mRNA levels of ATP-binding cassette (ABC) drug transporters (i.e., ABCC1–6 as well as ABCB1), previously shown to be CSC markers." (PMID 29036915, 2017). "Cancer cells may acquire resistance to chemotherapy through the hypoxia-induced expression of drug-pumping proteins, such as multidrug resistance 1 (MDR1)/p-glycoprotein (P-gp)/ABCB1, a known transcriptional target of HIF-1." (PMID 28042952, 2017). "Therefore, suppressing the activity or decreasing the expression of ABCB1 could restore the sensitivity of MDR cancer cells to chemotherapeutic agents and allow for successful chemotherapy in patients with MDR due to ABCB1-overexpression." (PMID 26824187, 2016). "To examine whether trametinib antagonizing ABCB1-mediated cancer MDR is owing to inhibition of the transporter activity of ABCB1, we measured the intracellular levels of two ABCB1 substrates rhodamine 123 and doxorubicin in the presence or absence of trametinib." (PMID 25915534, 2015). "As inhibition of the PI3K/AKT pathway may partially restore sensitivity to cisplatinum in cancer cells, this finding also explains the reason why afatinib could reverse the resistance to cisplatinum, which is not a substrate of ABCB1." (PMID 26317651, 2015). "ABCB1 expression reduced cancer cell sensibility to tozasertib but not to alisertib." (PMID 25268132, 2014). "Multidrug resistance protein 1 (MDR1/P-glycoprotein/ABCB1) and multidrug resistance-related protein 1 (MRP1/ABCC1), both belonging to the ATP-binding cassette superfamily of membrane-bound transporters, are two genes that are found to be highly related to multidrug-resistance of cancer cells." (PMID 24013781, 2013). "We observed synergistic effects of CDKi and DNR combinations in both carcinoma cell lines, but weaker than those detected in MDCKII-ABCB1 cells, probably because expression of ABCB1 mRNA is an order of magnitude weaker in HCT-8 and HepG2 cells than in MDCKII-ABCB1 cells." (PMID 24376706, 2013). "Therefore, ABCG2/BCRP as well as MDR1/ABCB1 plays a significant role in drug resistance, and inhibitors for ABCG2/BCRP may enhance the outcome of cancer chemotherapy." (PMID 22355323, 2012). "Overexpression of ABCB1 correlates with a negative prognosis in several types of cancer." (PMID 22460269, 2012). "Some selected genes with high discriminative ability, belonging to three cancer-relevant pathways, such as ATP-binding cassette (ABC) family of genes (ABCA4, ABCA8) were identified as prospective gene markers of lung AC other one (ABCB1, ABCC3 and ABCF2) should be also under serious consideration." (PMID 22369099, 2011). "To more closely examine the regulation of ABC transporter expression at concentrations similar to those in vivo, we established several single-step doxorubicin-selected clones with three different cancer cell lines and found that these clones did not express ABCB1." (PMID 18382425, 2008).
cancer (continued). "The overexpression of the ABCB1 (MDR1) gene product P-glycoprotein (P-gp) has been identified as an important mediator of multidrug resistance (MDR) to chemotherapeutic agents, which can lead to increased tumour resistance and worse prognosis in cancer patients." (PMID 17667922, 2007). "Importantly, this study demonstrated that CDK6 is a novel multi-functional target that may act as an on-off switch for ABCB1 expression, potentially reversing ABCB1-mediated MDR in cancers, and therefore, has significance in combination with cancer chemotherapy." (PMID 35459184, 2022). "Furthermore, our study provides the possible scenario in which the cancer cells might develop resistance to ARS-1620 via ABCB1 overexpression, and the possible solution for this scenario is the combination therapy of ARS-1620 with an ABCB1 inhibitor." (PMID 35281897, 2022). "Moreover, it is worth noting that erdafitinib did not alter the protein expression of ABCB1 in KB-V-1 or NCI-ADR-RES cancer cells, suggesting that ABCB1 may not be a major contributor to the development of erdafitinib resistance in cancer patients." (PMID 32466597, 2020). "It is worth noting that verapamil potentiated the in vitro toxicity of vincristine irrespective of the function or expression of ABCB1, which is consistent with previous reports demonstrating that verapamil at nontoxic concentrations amplifying the cytotoxicity of vincristine in cancer cell lines." (PMID 31941029, 2020). "Furthermore, EVs have been documented to carry drug efflux pumps such as P-glycoprotein 1 also known as multidrug resistance protein 1 (MDR1) or ATP-binding cassette sub-family B member 1 (ABCB1), ABCG2 or ABCA3 that facilitate the transfer of drug resistance to recipient cancer cells." (PMID 31146452, 2019). "Although various inhibitors/modulators of the ABCB1 and ABCG2 transporters have been well characterized, none of these compounds have been approved for cancer, due to limited clinical benefits, toxic effects and problematic adverse drug-drug interactions." (PMID 37521473, 2023). "It is exciting that ZSTK474 induced the degradation of multidrug efflux pumps ABCB1 and ABCG2 so as not to be affected by the efflux effect of resistant cancer cells." (PMID 35918352, 2022). "RNA isolation from co-cultures has confirmed that the mRNA pattern of ABCB1 and ABCG2 does not differ significantly between the various cancer cell line containing aggregates either in all cell type containing or in epithelial cell specific (CK7) calculations." (PMID 34065402, 2021). "Wnt5a increases cAMP response elements and TCF/LEF transcriptional activity, ABCB1 and chemoresistance in MDR cancer cells, suggesting that PKA dependent non-canonical Wnt signaling also regulates ABCB1 expression." (PMID 35582031, 2021). "Results showed that erdafitinib reverses multidrug resistance mediated by ABCB1, but not by ABCG2, in human cancer cell lines at subtoxic concentrations (<1 μM) and in a concentration-dependent manner." (PMID 32466597, 2020). "The EC16-1/saporin complex induces apoptosis in the parental cancer cells and in the resistant ABCB1- and ABCG2-overexpressing cells and does not significantly alter the intracellular localization of ABCB1 or ABCG2." (PMID 32098067, 2020). "In conclusion, our data indicated that ABCB1 and ABCG2 are unlikely to contribute significantly to the development of resistance to sitravatinib in cancer cells." (PMID 31941029, 2020). "Our results indicate that TMP195 attenuates the drug efflux function, but not the protein expression of ABCB1 and ABCG2 in cancer cells." (PMID 31905792, 2019). "In this study, we found that VS-4718, at non-toxic concentrations, significantly sensitized ABCB1- and ABCG2-overexpressing cancer cells to their substrates in a dose-dependent manner." (PMID 30425643, 2018). "The cancer cell lines HCC827, SW1573, KB-3-1 and HL-60, which showed high promoter methylation status of ABCB1, did not express ABCB1." (PMID 27689338, 2016).